NOX5 (NADPH oxidase 5)
Diseases named in the same sentence as NOX5 in open-access papers (continued):
Sharing a sentence is not in itself a finding about the gene and the disease.
tumor (continued). "Our results demonstrated that NOX5 stimulated the intratumoral ROS/Src/NF‐κB/cytokine axis to activate CAFs and further suggested the role of NOX5 as an oncogenic driver for the crosstalk between tumor and stroma." (PMID 34459125, 2021). "Because lactate contributes to stroma reprogram, and ROS increases the lactate secretion from tumor cells, we examined whether NOX5 could affect the concentration of extracellular lactate." (PMID 34459125, 2021). "Importantly, the staining of carbonic anhydrase IX (CA IX), a marker for tumor hypoxia was positively correlated with NOX5 in ESCC samples (cohort I)." (PMID 32792487, 2020). "To extend our in vitro observations, we investigated whether NOX5 could regulate tumor growth in vivo using the subcutaneous xenograft model." (PMID 32792487, 2020). "NOX5 expression could be thus contributing to conferring an invasive advantage to tumor cells." (PMID 36905456, 2023). "Moreover, NOX5 could be acting as a driving oncoprotein through the regulation of the expression of several cytokines to provide the conditions that facilitates tumor malignant progression." (PMID 36905456, 2023). "Furthermore, adding lactate to the CM of NOX5‐depleted ESCC cells could effectively restore the ability of tumor cells‐mediated CAFs activation." (PMID 34459125, 2021). "Additionally, we evaluated whether inhibition of Src activity can impair NOX5-mediated tumor progression." (PMID 32792487, 2020). "We further evaluated whether NOX5 could confer tumor cell ability of aggressiveness." (PMID 32792487, 2020). "Because tumor‐derived cytokines are crucial for the activation of CAFs,3, 18 we screened which cytokines secreted from ESCC cells were under the control of NOX5 using cytokine antibody array." (PMID 34459125, 2021). "We next investigated Nox5 protein levels in benign prostate and PCa tissue via immunohistochemical staining of a TMA comprising 3 tumor and 1 benign tissue cores each for 48 patients using a highly specific Nox5 antibody." (PMID 25559363, 2016). "Additionally, NADPH oxidase 5 (NOX5) is overexpressed in ESCC, activating intratumoral Src/NF-κB signaling, which stimulates tumor cells to secrete tumor necrosis factor-alpha (TNF-α), IL-1β, and lactate." (PMID 40134607, 2025). "In addition, in tumor cells, free fatty acids induce oxidative stress through NADPH oxidase 5 (NOX5); the increased ROS production contributes to the tumor cell invasion by activating the HIF1-MMP14 pathway." (PMID 36674430, 2023).
cardiovascular diseases (16 papers, 2014 to 2024). "The overexpression of Nox5 is closely associated with various cardiovascular diseases, including hypertension, aneurysms, and atherosclerosis." (PMID 39857372, 2024). "NOX5 has been implicated in cardiovascular diseases, such as coronary artery disease, atherosclerosis, and stroke as well as diabetic retinopathy, nephropathy, and vasculopathy." (PMID 34320175, 2022). "While both have strong connections to cardiovascular disease, a causal role for Nox5 remains ambiguous and would benefit from more focused investigation on SNPs with clear changes in activity." (PMID 24992705, 2014). "On the other hand, it would be also important to apply rigorous genetic methods to analyze NOX5 function in the pathogenesis of cardiovascular diseases." (PMID 37821487, 2023). "One of the earliest studies suggesting a link between vascular NOX5 and human cardiovascular disease was performed in coronary arteries in patients undergoing heart transplantation." (PMID 30334629, 2019). "While Nox1, Nox2, and Nox4 have been well characterized in models of cardiovascular disease, little is known about Nox5." (PMID 30334629, 2019). "The current study provides important resources that will facilitate investigation of a role of Nox5 in cardiovascular disease using rabbit models." (PMID 27486403, 2016). "Nox5 is present in the genomes of other species such as the rabbit that have broad utility as models of cardiovascular disease." (PMID 27486403, 2016). "This NOX5-derived MMP-10 secretion may have consequences in different cardiovascular diseases in vivo." (PMID 39456453, 2024). "Moreover, studies in human Nox5-expressing mice have highlighted a putative role for Nox5 in cardiovascular disease." (PMID 30334629, 2019). "Moving forward more studies will be necessary to determine the roles of the different signaling pathways discussed, as well as the potential therapeutic benefits of NOX5 inhibition in preventing growth factor-induced vascular SMC proliferation and migration associated with cardiovascular disease." (PMID 25144362, 2014). "The phylogenetic tree further suggests that monkeys would be the most closely related and therefore most appropriate animal model to study the role of Nox5-derived superoxide in cardiovascular disease, whereas rabbit and perhaps other models could be used when monkeys are impractical." (PMID 27486403, 2016). "The main aim was to analyze NOX5-mediated ROS effects in the UPR and its importance in cardiovascular diseases." (PMID 33572841, 2021). "Indeed, Nox5 expression is elevated in hypertension, post myocardial infarction, atherosclerosis and diabetes and may play an important role in human cardiovascular disease." (PMID 24992705, 2014). "Unlike its homologs, Nox5 can be activated by calcium ions without the need for additional subunits, making it a key enzyme in ROS generation in cardiovascular diseases." (PMID 39857372, 2024). "Recent studies have implicated upregulated Nox5-derived ROS in the aetiology of cardiovascular disorders (CVD), but the precise underlying mechanisms converging to Nox5 induction are not entirely elucidated." (PMID 31565149, 2019).
infection (9 papers, 2013 to 2023). The state of being infected such as from the introduction of a foreign agent such as serum, vaccine, antigenic substance or organism. "Finally, hCMEC/D3 infection with NOX5-encoding adenovirus promoted cell migration in the wound-healing assay." (PMID 36358519, 2022). "The expression of MSN was increased in NOX5-infected cells after 24 h of infection, and decreased after 48 h hours compared with GFP control cells." (PMID 36358519, 2022). "Although hCMEC/D3 cells infected with GFP adenovirus presented certain NOX5 mRNA levels, when NOX5 adenovirus was employed, it was increased 75,000 times after 12 h of infection." (PMID 36358519, 2022). "Firstly, AmpliFlu RedTM assay showed that NOX5-infected cells produced almost three times more extracellular H2O2 than control cells 24 h after infection." (PMID 36358519, 2022). "At protein level, NOX5 overexpression was greatly overexpressed 24, 48, and 72 h after infection in NOX5-infected cells." (PMID 36358519, 2022). "After 6 h of infection, NOX5 was already overexpressed, and its levels increased progressively over time, reaching a maximum 24 h after infection." (PMID 33572841, 2021). "After 12 h of infection, NOX5 was already overexpressed, and this effect was much more intense after 24 h." (PMID 32155782, 2020). "NOX5 infection of hCMEC/D3 generates a functional protein and an increase in ROS production." (PMID 36358519, 2022). "Protein levels of NOX5 were detected 6 h after infection and increased progressively over time." (PMID 33572841, 2021). "Co-silencing NOX5 and puc increased the median number of oocysts/midgut from 0 to 10 (p<0.0001; KS test) to the same level as the dsLacZ control, and the prevalence of infection from 22% to 88% (p<0.0001; χ2 test)." (PMID 24039583, 2013). "Over-activation of the JNK pathway, by silencing its suppressor Puckered, enhances midgut nitration and greatly reduces the intensity and prevalence of infection, an effect that is reverted by co-silencing HPX2, NOX5 or TEP1." (PMID 28729672, 2017). "The transcriptional induction of HPx2 in response to infection was more robust when puc was silenced, but NOX5 induction was no longer observed." (PMID 24039583, 2013).
renal disease (3 papers, 2019 to 2023). "Other forms of renal disease are also associated with increased NOX5 expression, including sepsis‐induced acute kidney injury (Ge, Huang, Zhu, Bian, & Pan, 2017) and metabolic disease‐related renal damage (Wan, Su, & Zhang, 2016)." (PMID 30801870, 2019). "More recently, we have shown that expression of human NOX5 in mice in a vascular smooth muscle/mesangial cell‐specific manner causes renal oxidative stress, glomerulosclerosis, mesangial expansion, renal inflammation and fibrosis, processes that accelerate progression of renal disease in diabetes." (PMID 30801870, 2019).
kidney (2 papers, 2016 to 2020). "In the context of human pathology, it appears that Nox5 is upregulated in the diabetic kidney and is the main source of renal ROS, indicating the key role of Nox5 in human DKD." (PMID 33396868, 2020).
adenocarcinoma (1 paper, 2020). A common cancer characterized by the presence of malignant glandular cells. "Interestingly, NF-κB is involved in NOX5-induced COX-2 activation in adenocarcinoma cells." (PMID 32155782, 2020). "Nevertheless, there is little information about the relationship between NOX5 and COX-2, only in adenocarcinoma cells and keratinocytes, with no information in vascular wall cells." (PMID 32155782, 2020).
NOX5 also shares sentences with these, for which no sentence is quoted: heart failure (4 papers); aneurysm (3); acute myocardial infarction (2); glomerulosclerosis (2); papillary thyroid cancer (2); pulmonary hypertension (2); renal failure (2); ventricular septal defect (2); age (1); aortic atherosclerosis (1); Barrett esophagus (1); cardiac ischemia (1); cervical cancer (1); colon adenocarcinoma (1); COVID-19 (1); fibrosis (1); fungal infections (1); gastroesophageal reflux disease (1); genetic diseases (1); Hirschsprung disease (1); Hyperoxaluria (1); hypothyroidism (1); hypoxia (1); liver fibrosis (1); lymphoma (1); male infertility (1); metabolic disease (1); multiple sclerosis (1); neuroblastoma (1); nevus (1).
A further 11 diseases each share a sentence with NOX5 in 1 paper.